GALR2 (galanin receptor 2)
Diseases named in the same sentence as GALR2 in open-access papers (continued):
Sharing a sentence is not in itself a finding about the gene and the disease.
Hypertension (1 paper, 2021). The presence of chronic increased pressure in the systemic arterial system. "Certain genes involved in the pathogenesis of hypertension—Alb, Chrm2, Xirp1, Kcnq1, Slc5a7, Kcnh1, Ache, Crlf1 and Galr2— should also be studied." (PMID 34603037, 2021).
hypopharyngeal cancers (1 paper, 2018). Carcinoma, predominantly squamous cell, arising from the epithelial cells of the hypopharynx. "The GALR2 gene methylation was significantly lower in hypopharyngeal cancers compared to laryngeal cancers and oral cavity cancers (p = 0.026 and p < 0.001, respectively)." (PMID 29361757, 2018). "Notably, the less frequently methylated genes (less than 30%) were as follows: CDH13, p16, MGMT, GAL, NPY, GALR2, and VEGFR3 for hypopharyngeal cancers; CDH13, p16, RASSF1A, GAL, NPY, and NPY1R for laryngeal cancers; and CDH13 and GAL for oral cavity cancers." (PMID 29361757, 2018).
injury (1 paper, 2012). Damage inflicted on the body as the direct or indirect result of an external force, with or without disruption of structural continuity. "In conclusion, Gal, via acivition of GalR1 and/or GalR2, may have neuoprotective effects in reducing neuropathic pain behaviors and improving nerve regeneration after nerve injury." (PMID 22624057, 2012).
ischemic stroke (1 paper, 2017). A stroke disorder caused by obstruction of blood flow to the brain, due to thrombotic (local blood clot formation) or embolic (due to a blood clot or other material traveling from another site) event. "In order to determine whether manipulating GalR2 expression levels in primary cultured neurons would affect GAL’s role in ischemic stroke, lentiviral knockdown of GalR2 in primary cultured neurons was utilized." (PMID 28203483, 2017).
liver cancer (1 paper, 2025). An epithelial or non-epithelial malignant neoplasm that arises from the liver. "Moreover, anti-apoptotic and anti-proliferative effects of galanin and GALP were shown to be mediated through GalR2, which can explain no liver cancer development in mice under the CEL treatment." (PMID 39968178, 2025).
liver fibrosis (1 paper, 2022). "Inhibition of Gal1R and GalR2 in Mdr2−/− mice reduced IBDM and the expression of fibrosis markers, whereas GalR2 antagonist (M871) only attenuated liver fibrosis without changing IBDM, suggesting that the promotion of HSCs activation and fibrosis gene expression by galanin is mediated by Gal2R." (PMID 36497043, 2022).
mononeuropathy (1 paper, 2017). Disease or trauma involving a single peripheral nerve in isolation, or out of proportion to evidence of diffuse peripheral nerve dysfunction. "There was a significant increase in the content of galanin receptor 2 in ACC of rats with mononeuropathy (t = 5.80, P < 0.001) than that in normal rats tested by western blot." (PMID 28378856, 2017). "The present study was performed to explore the role of galanin in nociceptive modulation in ACC of normal rats and rats with mononeuropathy, and further to explore the plastic changes in the expression of galanin and galanin receptor 2 in ACC in rats with mononeuropathy." (PMID 28378856, 2017). "And there may be plastic changes in the expression of galanin and galanin receptor 2 in rats with mononeuropathy, as well as in the galanin-induced antinociception." (PMID 28378856, 2017). "Moreover, both the mRNA levels of galanin receptor 2 and the content of galanin receptor 2 in ACC increased significantly in rats with mononeuropathy than that in normal rats." (PMID 28378856, 2017). "Combining the behavioral tests with these results indicate that there may be plasticity in the expression of galanin and galanin receptor 2 in rats with mononeuropathy, as well as in the galanin-induced antinociception." (PMID 28378856, 2017). "The present study was performed to explore the role of galanin and galanin receptor 2 in nociceptive modulation in anterior cingulate cortex (ACC) of normal rats and rats with mononeuropathy." (PMID 28378856, 2017). "Our results have demonstrated that galanin receptor 2 is involved in the galanin-induced antinociception in the ACC in normal rats and rats with mononeuropathy." (PMID 28378856, 2017). "There was a significant increase in the mRNA level of galanin receptor 2 (t = 9.77, P < 0.001) in ACC in rats with mononeuropathy than that in normal rats tested by RT-PCR." (PMID 28378856, 2017). "Moreover, both the mRNA level of galanin receptor 2 and the content of galanin receptor 2 in ACC increased significantly in rats with mononeuropathy than that in normal rats." (PMID 28378856, 2017).
oropharyngeal cancers (1 paper, 2017). Carcinoma, predominantly squamous cell, arising from the epithelial cells of the oropharynx. "In oropharyngeal cancers, the odds ratio for recurrence is higher when the GALR2 promoter is methylated versus unmethylated." (PMID 29100314, 2017).
prostate carcinoma (1 paper, 2008). A carcinoma that arises from epithelial cells of the prostate gland. "Compared to adjacent normal prostate, all 8 genes had significantly higher methylation in prostate cancer by t-test analysis (P<0.001 for NKX2-5; P<0.001 for SPOCK2; P = 0.004 for GALR2; P<0.001 for CLSTN1; P<0.001 for NSE1; P<0.001 for DPYS; P = 0.019 for FOXN4; P<0.001 for SLC16A12)." (PMID 18446232, 2008).
prostate tumor (1 paper, 2022). "In the obese prostate tumor, when receptor GALR2 receives a high concentration of galanin ligand, the galanin activates receptor GALR2 to increase human food intake and indirectly promote fat intake." (PMID 35164166, 2022).
sciatic neuropathy (1 paper, 2021). Disease or damage involving the SCIATIC NERVE, which divides into the PERONEAL NERVE and TIBIAL NERVE (see also PERONEAL NEUROPATHIES and TIBIAL NEUROPATHY). "In the present study, we use the M1145 and M871 to investigate whether GalR2 activation plays an antinociceptive effect in NAc of rats with experimental sciatic neuropathy." (PMID 33546583, 2021). "We first investigated whether the GalR2 was activated in NAc of rats with sciatic neuropathy." (PMID 33546583, 2021).
ulcer disease (1 paper, 2016). A lesion on the surface of the skin or a mucous surface, produced by the sloughing of inflammatory necrotic tissue. "Although we have not observed statistically significant changes in the expression of GalR2 in the pyloric wall tissue of the experimental pigs, its participation in the regulation of the pyloric activity during ulcer disease cannot be excluded." (PMID 27175780, 2016).
tumor (21 papers, 2002 to 2024). "SST hypermethylation, with subsequent decrease in gene expression, has been observed in 81% of HNSCC samples and has been linked to tumor extent, disease stage, galanin type 2 receptor (GALR2) methylation, and tachykinin-1 (TAC1) methylation." (PMID 36769317, 2023). "Generally, Gal receptor 1 (GalR1) is involved in tumor suppression and exerts antiproliferative actions, whereas activation of GalR2 induces antiproliferative or proliferative effects in HN SCCs." (PMID 39906323, 2024). "One of the signaling receptors on tumor cells associated with cell migration and PNI is Galanin receptors 2 (GALR2), which is thought to play a very important role in regulating PNI in HNSCC." (PMID 36982894, 2023). "SSTR1 hypermethylation has been detected in 64% of HNSCC samples and has also been associated with tumor extent, disease stage, SST hypermethylation, and increased expression of galanin (GAL), GALR2, TAC1, and tachykinin type 1 receptor (TACR1)." (PMID 36769317, 2023). "In conclusion, our findings demonstrated that the GAL/GALR2 axis promoted SACC‐PNI via modulating tumor cell EMT." (PMID 36039037, 2023). "Galanin plays an important role in perineural invasion, and there appears to exist a positive feedback loop (autocrine and paracrine) of GALR2 activation in the tumor microenvironment that stimulates and sustains tumor growth and invasion." (PMID 35267186, 2022). "GALR2 activation subsequently induces tumor cells to secrete pro-inflammatory mediators and neuropeptides that promote invasion and PNI through NFATC2 (nuclear factor of activated T cells 2)-mediated cyclooxygenase-2 expression." (PMID 34885121, 2021). "SST methylation in 81% of HNSCC tumor specimens significantly correlated with tumor size (P = 0.043), stage (P = 0.008), galanin receptor type 2 (GALR2) methylation (P = 0.041), and tachykinin-1 (TAC1) (P = 0.040)." (PMID 25734919, 2015). "Methylation of SST was associated with several clinicopathologic factors, including tumor size (P = 0.043), stage (P = 0.008), GALR2 methylation (P = 0.041), TAC1 methylation (P = 0.040), and DAPK methylation (P = 0.012) (Table 1and S1 Table)." (PMID 25734919, 2015). "SSTR1 methylation was significantly correlated with tumor size, stage, and methylation of galanin, GALR2, TAC1, TAC1R, H-cadherin, MGMT, DAPK, and DCC methylation." (PMID 26251921, 2015). "Conversely, GalR2 may inhibit tumor cell proliferation and induce caspase-3-dependent apoptotic mechanisms." (PMID 39906323, 2024). "Therefore, targeting the GalR2-induced pathway or blocking Gal offers a promising clinical strategy for disrupting the neural-tumor crosstalk in PNI, potentially improving treatment outcomes of HNC patients." (PMID 39906323, 2024). "The average immunoreactivity of GALR1 and GALR3 in muscularis externa plexuses close to the CRC tissue was slightly reduced as compared to the plexuses distant from the tumour, while GALR2 immunoreactivity reminded unchanged (p = 0.0351, p = 0.0204 and p = 0.1109, respectively)." (PMID 36551197, 2022). "Furthermore, they show that downregulation or blockage of GALR2 or galanin disrupted this nerve-tumor crosstalk to prevent PNI and neuritogenesis." (PMID 34885121, 2021). "Recent studies claim that GAL and GALR2 play a significant role in nerve-tumor interactions." (PMID 29854027, 2018). "Similar to the intersection between neural and tumor cells, the results of this study suggest that galanin mediates crosstalk between tumor and immune cells via GALR2, which may favor tumor growth and invasion by facilitating immune-escape and co-opting immune cells." (PMID 35267186, 2022). "It is tempting to speculate that the immunosuppressive effects of galanin via GALR2 may represent another example of crosstalk between neoplastic/neuronal/immune cells in the tumor microenvironment that facilitates immune evasion and even co-opts immune cells to enhance tumor growth and invasion." (PMID 35267186, 2022).
tumor (continued). "Overexpression of GALR2 stimulated cell proliferation and survival through ERK and Akt activation in vitro and promoted tumor growth in vivo." (PMID 34885121, 2021). "Recent studies have provided strong evidence supporting the tumor suppressive effects of galanin, GALR1, and GALR2, and they suggested that the inhibition of cell proliferation and apoptosis by galanin occurred via its receptors." (PMID 29462183, 2018). "Methylation of SST was significantly related to several clinicopathologic factors, including tumor size, stage, DAPK methylation, TAC1 methylation, and GALR2 methylation." (PMID 26251921, 2015). "SSTR1 hypermethylation in 64% of cases was correlated with tumor size (P = 0.037), stage (P = 0.037), SST methylation (P < 0.001), and expression of galanin (P = 0.03), GALR2 (P = 0.014), TAC1 (P = 0.023), and tachykinin receptor type 1 (TACR1) (P = 0.003)." (PMID 25734919, 2015). "In vivo, GALR2 induces invasion of HNSCC cells via NFATC2-mediated transcription of cyclooxygenase-2, which enzymatically facilitates prostaglandin E2 production, thereby promoting tumor progression." (PMID 35267186, 2022). "Our previous study showed that the expression of GALRs proteins was higher in CRC tissue, than in unchanged mucosa cells distantly located from the tumour (GALR2 was not significant, but the tendency was noticed)." (PMID 36551197, 2022).
cancer (11 papers, 2008 to 2025). A tumor composed of atypical neoplastic, often pleomorphic cells that invade other tissues. "Several studies have reported that the role of GALR2 in various cancers involves angiogenesis promotion, inhibition of cancer proliferation, induction of apoptosis and facilitation of perineural invasion." (PMID 40836964, 2025). "GALR2, a receptor for galanin, is expressed in many normal tissues and several cancers." (PMID 40836964, 2025). "GALR2 has been investigated as potential prognostic factor in several cancer types." (PMID 26251921, 2015). "In addition, influenced by the activation of receptor GALR2, TF MYOCD is upregulated after the signal is transmitted into the nucleus, which causes the development and differentiation of smooth muscle, indirectly promoting the migration of cancer cells." (PMID 35164166, 2022). "The promoter methylation status of GALR2 was analyzed in cancer tissues from 36 patients and paired noncancerous mucosae using quantitative methylation-specific PCR." (PMID 26251921, 2015). "Cluster 2 contains instead receptor-ligand axes that are more frequently concordantly downregulated in cancer subtypes, although several of these might still be concordantly upregulated in specific subtypes (e.g., CXCR2, EDNRB, FFPR2, or LGR6, GALR2, and UTS2R)." (PMID 38723607, 2024). "We found that GALR1, GALR2 and GALR3 relative immunoreactivity (comparing myenteric plexuses close to CRC cells vs. plexuses distant from cancer invasion) did not correlate with the overall survival of CRC patients." (PMID 36551197, 2022). "We found that GALR1, but not GALR2 and GALR3, relative immunoreactivity (comparing submucosal plexuses close to CRC cells vs. plexuses distant from cancer invasion) correlate with the overall survival of CRC patients (p = 0.0115 and HR = 4.97) and clinical-pathological data of CRC patients." (PMID 36551197, 2022).
neurodegenerative disease (3 papers, 2018 to 2023). A disorder of the central nervous system characterized by gradual and progressive loss of neural tissue and neurologic function. "Further research is required to explore the potential role of GALR2 and Y1R agonists intranasal administration in cell replacement‐based strategies in neurodegenerative diseases affecting SVZ neurogenesis." (PMID 36599082, 2023).
heart disease (2 papers, 2022 to 2025). "In summary, these findings unravel new insights into the role of galanin/GalR2 axis in the heart and suggest novel therapeutic strategies in heart disease." (PMID 35431947, 2022). "Therefore, the authors concluded that targeting GalR2 might offer novel therapeutic strategies for heart diseases." (PMID 39968178, 2025).
GALR2 also shares sentences with these, for which no sentence is quoted: glioma (3 papers); multiple sclerosis (3); brain diseases (2); mood disorder (2); phaeochromocytomas (2); pituitary adenoma (2); Xanthelasma (2); age (1); Alzheimer disease (1); amnesia (1); anaplastic oligoastrocytoma (1); Arrhythmia (1); astrocytic tumor (1); astrocytoma (1); cholestasis (1); cognitive deficits (1); Crohn disease (1); diabetes (1); diabetic cardiomyopathy (1); dysentery (1); endometrial cancer (1); experimental autoimmune encephalomyelitis (1); ganglioglioma (1); glioblastoma multiforme (1); Hepatic steatosis (1); hepatoma (1); Hyperglycemia (1); hypertrophy (1); laryngeal carcinoma (1); lung adenocarcinoma (1).
A further 17 diseases each share a sentence with GALR2 in 1 paper.